EGF (epidermal growth factor)
Diseases named in the same sentence as EGF in open-access papers (continued):
Sharing a sentence is not in itself a finding about the gene and the disease.
tumor (continued). "The possible biological mechanism may be as follows: tumor cells can secrete colony-stimulating factor and attract macrophages, which in turn secrete epidermal growth factor to guide tumor cells toward blood vessels." (PMID 38129820, 2023). "Several tumor initiating and/or promoting pathways including epidermal growth factor (EGF) and vascular endothelial growth factor-mediated signaling pathways activate the RAS-MAP kinase cascade for ITGB1 transcription through downstream AP-1 family transcription factors." (PMID 37398311, 2023). "EGF signaling was uniquely upregulated in tumor-localized MFAP5 + fibroblasts." (PMID 37344903, 2023). "MYL1 facilitates tumor metastasis and correlates with tumor immune infiltration in HNSCC and these effects may be associated with the EGF/EGFR pathway." (PMID 37679666, 2023). "Here, we found that the TRPV1 is overexpressed by NANOG in cisplatin-resistant tumor cells and mediates Ca2+ influx and subsequent increases in autophagic EGF secretion, which activates the EGFR-AKT signaling pathway consequently contributing to cisplatin resistance." (PMID 37165076, 2023). "One could therefore speculate that in vivo they might be less responsive to EGF being secreted by macrophages in the tumour microenvironment and could therefore be less invasive." (PMID 37803333, 2023). "Since EGF is a significant positive regulator of tumor growth, the disruption of receptor-depending clearance of such tumor-supportive factor by chemotherapeutic drug may lead to the macrophage-mediated homeostatic imbalance in TME." (PMID 36960065, 2023). "Overall, MYL1 facilitates tumor metastasis and correlates with tumor immune infiltration in HNSCC and these effects may be associated with the EGF/EGFR pathway." (PMID 37679666, 2023). "EGF through paracrine stimulation of normal endothelial promotes tumor neovascularization." (PMID 36594087, 2023). "Thus, our results indicate that TRPV1 by itself was sufficient to induce the cisplatin resistance of tumor cells via EGF-EGFR signaling pathway." (PMID 37165076, 2023). "Also, the tumor cells affect the macrophage cells by releasing the CSF-1 and increasing the macrophage recruitment and EGF secretion that facilitate the tumor cell's chemotaxis into the blood vessels." (PMID 38017494, 2023). "Furthermore, we show that the EGF pathway facilitates tumor-promoting metabolic programs by elevating the steady-state expression of CSN6/FASN in CRC cells." (PMID 37202390, 2023). "Since tumor angiogenesis is primarily caused by induction of an angiogenic switch (from a quiescent state to a proliferative vasculature) through secretion of angiogenesis-stimulating growth factors, HUVECs were treated with 10 ng/mL VEGF or EGF." (PMID 37723574, 2023). "Therefore, it was surprising to see that a high frequency of GARPNU+ tumor cells was linked to reduced overall survival, despite the observed upregulation of GARPNU+ in differentiation-promoting conditions (NB-bFGF/-EGF)." (PMID 38136258, 2023). "EGF primarily binds to the surface of GBMs to promote tumor invasion." (PMID 36969167, 2023). "One of the experiments evaluated the tumor cell migration guided by EGF-loaded microcapsules." (PMID 37241602, 2023). "Induction of GSK3β inactivation by EGF in tumor cells leads to increased glycosylation PD-L1." (PMID 37554324, 2023). "In the tumor microenvironment, several growth factors such as EGF and VEGF are overexpressed." (PMID 37723574, 2023). "M2-TAMs can directly stimulate tumor cell proliferation and invasion and suppress T cell recruitment and activation through the production of cytokines, such as interleukin (IL)-10 or epidermal growth factor (EGF)." (PMID 37402945, 2023). "As we have shown by western blot, in trap mice are the levels of ERBB ligands TGFA and EGF only reduced and not deleted, but this seems to be sufficient enough to reduce tumor growth and does not cause side effects." (PMID 37341059, 2023).
tumor (continued). "CAFs secrete soluble factors, which include cytokines, chemokines, and growth factors such as interleukin 6 (IL-6), C-type lectin domain family 3 member B (CLEC3B), C-X-C motif chemokine 12 (CXCL12), and epidermal growth factor (EGF) to transform the TME to support tumor growth." (PMID 37469395, 2023). "The expression of EGF by TAMs may be adversely affected by CSF-1 synthesized by tumor cells, which may enhance the metastatic potential of tumor cells." (PMID 38033495, 2023). "PMs can be switched to tumor-associated macrophages (TAMs) in ascites with pro-tumor effect by releasing various soluble mediators, including IL-6, IL-10, CCL18, CCL22, TNF-α, TGF-β, and EGF that triggers pro-tumorigenic signaling pathways in tumor cells and infiltrating leukocytes in the TME." (PMID 37932814, 2023). "Moreover, normal peritumoral cells cross-talk with tumor cells, supplying them with growth factors, such as EGF, IGF-2, FGF, transforming growth factor-beta (TGF-beta), human platelet-derived growth factor (PDGF) and VEGF, as well as regulating their motility." (PMID 37296944, 2023). "Notably, EGF plays crucial roles in tumor angiogenesis thanks to its ability to generate a favorable environment for the development of cancer vasculature." (PMID 37175811, 2023). "At present, TAMs are believed to play three different roles in promoting tumor growth and metastasis: first; TAMs promote tumor cell invasion into the vasculature through MCSF-1 from tumor cells and epidermal growth factor (EGF) from macrophages and their receptors, thereby promoting tumor spread." (PMID 37206921, 2023). "Signals that induce EMT (EGF, HGF, TGF-β, and PDGF) are produced by tumor-associated stroma and are accountable for promoting functional activation in malignment cell of EMT-inducing transcription factors (Snail, Slug, zinc finger E-box bind-ing homeobox 1 (ZEB1), Twist, Goosecoid, and FOXC2)." (PMID 37609398, 2023). "Finally, Clever-1 on TAMs was recently shown to be responsible for epidermal growth factor (EGF) clearance, a highly relevant tumor promoter." (PMID 38116017, 2023). "EGF plays a significant role in tumor cell proliferation and signal transduction." (PMID 37990309, 2023). "Hence, surface modification of NPs with EGF can significantly improve drug uptake by tumor cells and increase its concentration in tumor tissues through ligand-receptor-specific binding." (PMID 35156493, 2022). "Whereas VEGF is regarded as the most important mediator of tumor angiogenesis through the stimulation vascular endothelial cell proliferation, migration, survival etc., EGF is important for the regulation of intestinal epithelial cell growth, e.g. during wound healing, but also tumor development." (PMID 35280747, 2022). "EGFR encodes a receptor for EGF, which is significant for GBM tumor development." (PMID 36291290, 2022). "Secondly, a great deal of findings reported that CAFs could accelerate tumor growth by producing epidermal growth factor (EGF), fibroblast growth factor (FGF), hepatocyte growth factor (HGF), cytokines and chemokines." (PMID 36093115, 2022). "NEU promotes the formation of blood vessels and tumor growth by secreting vascular growth factors; It is also possible to accelerate tumor progression by promoting the release of proteins such as epidermal growth factor and platelet-derived growth factor in extracellular matrix." (PMID 35693305, 2022). "Also, the poor prognosis of cancer has been correlated with the upregulation of S100A4 in tumor cells, and its expression has been regulated by other factors like β-catenin, epidermal growth factor, tumor necrosis factor alpha (TNF-α), and methylation." (PMID 35965620, 2022). "In addition to EGF-secreted action on tumor cell proliferation and survival, studies shows that secreted EGF also plays a crucial role in M2 polarization in cancer." (PMID 36325334, 2022).
tumor (continued). "Studies in cancer have shown that integrin signaling can mediate the activation of the EMT program induced by other factors present in the tumor microenvironment, such as the epidermal growth factor (EGF), the fibroblast growth factor (FGF), and the pituitary tumor-transforming gene (PTTG)." (PMID 35682554, 2022). "Tumor-associated macrophages (TAMs) regulate inflammation and initiate, facilitate, or inhibit cancer development by affecting other immune cells and producing various factors, including nitric oxide, VEGF, EGF, and TGF-β." (PMID 35493077, 2022). "Within the large spheroids, EGFR+ tumor cells surrounded the central EGF+ macrophages." (PMID 35682890, 2022). "S1P, acting as an oncopromotor, is involved in tumour growth and invasiveness; some of these effects have been attributed to its ability to regulate the expression of many growth factors, including epidermal growth factor (EGF)." (PMID 35806446, 2022). "The identification of Y976 phosphorylation coupled with EGF signaling may pave the way for limiting uncontrolled cancer cell proliferation as well as tumor growth by blocking PKM2 functions." (PMID 35931120, 2022). "Also, the EGF@DOX-NPs significantly inhibited tumor growth in vivo, increasing the survival of the tumor-bearing mice without apparent systemic toxic effects through RT-induced aggregation." (PMID 35156493, 2022). "Indeed, we found that targeting MNX1-AS1 abolished EGF-stimulated PKM2 nuclear translocation with robust inhibition of tumor growth observed in vitro and in vivo." (PMID 36476366, 2022). "The tumor-cell–macrophage paired chemotaxis is driven by a paracrine loop between tumor-cell-secreted colony-stimulating factor 1 (CSF-1) and macrophage-secreted epidermal growth factor (EGF)." (PMID 35565297, 2022). "Not only this, although the docetaxel treatment reduces EGFR activation by inhibiting its being phosphorylated in the presence of EGF, the abnormal activation, mutation, and overexpression of EGFR played a vital role in the establishment of docetaxel resistance in tumor cells as well as PCa cells." (PMID 36338727, 2022). "To further confirm Kindlin-2 involvement in mammary epithelial cells to regulate tumor growth, we isolated mammary epithelial cells from wild-type or K2-deficient mice and treated them with either TGF-β or EGF, and subsequently measured their activation of either SMAD3 or ERK1/2, respectively." (PMID 35158908, 2022). "Examples of cytokine-receptor pairs implicated in MSC tumour tropism are SDF-1 & C-X-C motif chemokine receptor-4 (CXCR4), VEGF & VEGFR, MCP-1 & C-C motif chemokine receptor (CCR2), epidermal growth factor (EGF) & EGFR, and hepatocyte growth factor (HGF) & c-Met." (PMID 35103937, 2022). "In particular, in PCa pSTAT-3 and IL-6R are present in 95% of metastatic niches of patients who die of castration-resistant PCa (CRPC); this suggests that in PCa, the activation of STAT-3 mediated by IL-6, IL-10 and EGF serves an important role for tumor progression and development of metastasis." (PMID 35703345, 2022). "As the pathogenesis, the crossed reactions between tumor antigens and growth factor receptors on epidermal cells and/or the cutaneous changes by the action of epidermal growth factor, transforming growth factor alpha and insulin-like growth factor secreted by the tumor cells are proposed." (PMID 35713794, 2022). "For example, by secreting an abundance of pro-tumorigenic proteases, cytokines and growth factors, TAMs support a variety of behaviors within the primary tumor, such as growth, angiogenesis and invasion (e.g., EGF, which participates in a paracrine signaling loop via tumor-secreted CSF-1)." (PMID 36139552, 2022). "“Angiogenic switch” activators are the tumor microenvironment; mutation in oncogenes or tumor-suppressor genes; pro-angiogenic molecules (VEGF, FGF-2, EGF, PDGF, PIGF, and MMPs); and anti-angiogenic factors (thrombospondin, angiostatin, tumstatin, and endostatin)." (PMID 35454076, 2022).
tumor (continued). "Treatment of the co-culture with EGF enhanced brain tissue invasion of the tumor cells." (PMID 35941177, 2022). "Investigators have also assessed can whether the difference between metabolism of GSCs and tumor cells depended on responses to EGF and basic FGF (bFGF) in the media." (PMID 35956937, 2022). "Moreover, the expression of the EGFR ligands heparin-binding EGF (Hbegf), amphiregulin (Areg) and epiregulin (Ereg) was also markedly elevated in tumor tissues." (PMID 35619118, 2022). "TAMs may directly promote tumor cell proliferation through the production of growth factors, like epidermal growth factor (EGF) which induces proliferation and supports epithelial-mesenchymal transition in tumor cells." (PMID 36439180, 2022). "The role of GBP-2 in cancers may be either tumor type specific and/or EGF versus IFN-γ environment driven." (PMID 35681772, 2022). "We have previously validated this system using knockdown of lin-3/EGF (required in mesoderm) and lin-39/Hox (required in VPCs), and used this system to identify genes that, when knocked down, behave in a tumor-suppressor-like manner and enhance VPC proliferation in mutants lacking gap-1." (PMID 35929788, 2022). "Our findings suggest in principle that EGF-displayed/targeted λ phages may be valuable in delivery of toxic therapeutics of interventions that may release activity of local anti-tumor responses or immune checkpoint inhibitors." (PMID 36591314, 2022). "Additionally, cytokines and growth factors in the TME, particularly IL-6, EGF, and hepatocyte growth factor, suppress anoikis by activating tumor cell signaling pathways, including the RAS-MAPK, PI3K-mechanistic target of rapamycin kinase, and STAT3 pathways." (PMID 36010693, 2022). "Similarly, IONPs induce elevation in MSC EGFR and this supports MSC tumour tropism (towards tumour EGF)." (PMID 35103937, 2022). "The tumor cell proliferation was greatly inhibited in the RT + EGF@DOX-NPs group." (PMID 35156493, 2022). "However, encapsulation of DOX in nanoparticles and EGF modification significantly decreased the accumulation of the drug in the cardiac tissues and increased its content in the tumor tissues (0.11 ± 0.07 μg/mL of free DOX vs 0.32 ± 0.10 μg/mL of EGF@DOX-NPs)." (PMID 35156493, 2022). "OTR overexpression-induced metastasis might thus be associated with EGF in the tumour microenvironment, which was investigated by replacing 10% FBS with EGF (20 ng/mL) as the chemoattractant in the transwell migration assay." (PMID 35884900, 2022). "Ongoing studies suggest that mesothelial/OCC induce production of FGFs and EGF growth factors in mesothelial cells that may create a paracrine loop that enables tumor cell growth and invasion." (PMID 33450985, 2021). "M2-like cells release cytokines IL-4, IL-10, IL-13, and growth factors TGF-β, vascular endothelial growth factor (VEGF), epidermal growth factor (EGF), which exhibit pro-tumorigenic properties: stimulate cell proliferation, tumor encapsulation, and vasculogenesis and promote drug resistance." (PMID 33800829, 2021). "EGF promotes DNA synthesis, regeneration, tumor growth, and the progression of tumor cells." (PMID 34572344, 2021). "Since chemokines and cytokines including CCLs (chemokine (C-C motif) ligands), CXCLs (Chemokine (C-X-C motif) ligands), EGF and CSFs (Colony stimulating factors) are important drivers for macrophage recruitment 27, 28, we examined their expression in tumor cells upon ILT4 knockdown." (PMID 33537094, 2021). "In this regard, the clinical application of EGF treatment may be a possible approach to reduce the excessive activity of EGFR in inducing tumor proliferation." (PMID 33898431, 2021). "The impact of age, tumour location and serum EGF on overall survival of oncological patients." (PMID 34115785, 2021). "Tumor invasion is promoted by substrates and tumor aggregation factors, such as EGF." (PMID 34639167, 2021).
tumor (continued). "CAF secrete epidermal growth factor and insulin-like growth factor-1, which promote tumor growth." (PMID 34563225, 2021). "It had been widely proposed that PTEN functions as a tumor suppressor through its lipid phosphatase activity, but these results further suggested that the protein phosphatase activity of PTEN is also important for the tumor suppressor function, through controlling the duration of EGF signaling." (PMID 34572553, 2021). "Tumor-associated macrophages (TAMs) have features of the M2 macrophages and promote angiogenesis in tumors by secreting proangiogenic cytokines (e.g., VEGF, epidermal growth factor [EGF], FGFs and Ang-1), MMP proteases, plasmin, and plasminogen activator." (PMID 34209508, 2021). "Therefore, combining CNTs with EGF endows CNTs with tumor-targeting ability and can be regarded as another method to improve therapeutic efficacy of anticancer treatment." (PMID 34915901, 2021). "The mechanism of EGFR upregulation in tumor endothelial cells could be attributed to EGF secreted by cancer cells." (PMID 34680445, 2021). "Oncogenic EGF and substrate stiffening resembled tumour-specific microenvironmental changes." (PMID 33921304, 2021). "In other solid cancers, neutrophils support tumour growth by contributing to genetic instability by releasing reactive oxygen species (ROS) and secreting growth factors, such as epidermal growth factor (EGF), hepatocyte growth factor (HGF), and platelet-derived growth factor (PDGF)." (PMID 34830780, 2021). "Moreover, TGF-β is a major inducer of EMT since it can interact with other growth factors, such as epidermal growth factor (EGF), to influence the malignant transformation of CSCs and tumor-associated stromal fibrosis." (PMID 34371753, 2021). "As EGF is essential for wound healing and tissue repair, our findings also suggest that for several weeks following the tumor removal surgery the remaining tumor could be under the control of endogenous EGF." (PMID 33748471, 2021). "This association has been attributed to the role of the tumor microenvironment, as in vitro studies indicate that several platelet-derived growth factors (PDGF, EGF and serotonin) stimulate the expression of HCC cells and blunt the action of antiangiogenetic drugs such as Sorafenib and Regorafenib." (PMID 34072309, 2021). "In contrast to the highlighted positive effects of SCFAs, the bacterial metabolite butyric acid plays a role in exacerbating ameloblastoma, a benign tumour of the jawbone, through interactions with epidermal growth factor and transforming growth factor β1 secreted by the tumour cells." (PMID 33673140, 2021). "Likewise, the EGF moiety of Fcy-hEGF will transform the passive liposome into active one specific for EGFR-overexpressing tumor." (PMID 33672989, 2021). "Eosinophils, as TAMs, are also able to infiltrate tumors and influence tumor progression, inhibiting tumor growth by secreting IL-10 and IL-12, or promoting it by secreting growth factors such as epidermal growth factor (EGF) and transforming growth factor-b1 (TGF-b1)." (PMID 34830940, 2021). "Furthermore, the results observed for the group of animals treated with the 10 min laser irradiation combined with EGF-conjugated HAOA-coated GNPs showed a tumor reduction of around 43%." (PMID 33808293, 2021). "Nevertheless, it seems plausible that EGF could have a biological role in the tumor growth, and therefore subsequent studies should include patients treated with EGFR antagonists as well." (PMID 34115785, 2021). "While the EGFR-specific Fab blocks EGF signaling, the PD-L1-specific Fab can inhibit immune checkpoints and, in combination, both could facilitate an enhanced tumor selectivity." (PMID 34040611, 2021). "Thus, incorporating endothelial or endothelial progenitor cells along with key angiogenic factors such as VEGF or EGF in stromal bioink is crucial for recapitulating tumor growth." (PMID 33493799, 2021).